LEP (leptin)
Diseases named in the same sentence as LEP in open-access papers (continued):
Sharing a sentence is not in itself a finding about the gene and the disease.
Obesity (continued). "When taken together the results of the present study suggest that adipocytes in non-obese subjects may function as salutary anti-hypertrophic factors, a property reflecting a favourable leptin to adiponectin balance, which is compromised in obesity due to adipocyte remodelling." (PMID 26731409, 2016). "Thus, promoting the secretion of adiponectin, reducing insulin resistance and leptin level may be an important mechanism for the anti-obesity and hypoglycemic effects of P. trifoliata extracts." (PMID 27058520, 2016). "WAT releases hormones (leptin, adiponectin, etc.)and cytokines (tumor necrosis factor-α (TNF-α), interleukin 6 (Il-6), monocyte chemoattractant protein-1 (Mcp-1), etc.)that modulate whole-body metabolism, insulin resistance, and the systemic low-grade inflammation associated with obesity." (PMID 28105413, 2016). "In addition, FRG was observed to homeostasis about anti-obesity and regulating leptin.." (PMID 27322312, 2016). "Our results suggest that acquired resistance to leptin and insulin, rather than high levels of these hormones in the circulation, may have a causal role underlying the epidemiological correlation between obesity and cancer risk." (PMID 27842582, 2016). "Gestational nicotine exposure may not cause obesity and type 2 diabetes in first-generation offspring but instead may moderately enhance central leptin-melanocortinergic regulation of energy and glucose balance via POMC neurons." (PMID 27609221, 2016). "Importantly, the major difference between the lipodystrophy syndromes and their associated metabolic abnormality and obesity is the decrease in adipose tissue with low levels of leptin in lipodystrophy, whereas obesity is characterized by an excess of adipose tissue and increased leptin levels." (PMID 27649157, 2016). "In this study, obesity and glucose intolerance were evident after 8-weeks feeding with high-fat diet, which is indicated by significantly increased body weight, elevated fasting blood glucose level, higher plasma leptin and insulin concentrations, as well as diminished oral glucose tolerance." (PMID 27528227, 2016). "For instance, while increased expression of hypothalamic Socs3 and Lrgrp are hallmark features of diet-induced obesity and key factors in the development of common leptin resistance, the expression of these genes is not altered or tended to be lower in BBS mice." (PMID 26926121, 2016). "In ANOVA modeling, leptin concentrations in SF and SOCS-3 expression in cartilage significantly explained levels of SF MMP-1 and MMP-3 in the obese but not in the non-obese group pointing to obesity-related association of leptin and SOCS-3 in OA pathophysiology." (PMID 27716333, 2016). "Mature adipocytes are not only a lipid storage site but also produce and secrete different adipokines and factors such as leptin, interleukin (IL)-6, and vascular endothelial growth factor (VEGF), which are closely associated with angiogenesis and other pathological conditions in obesity." (PMID 27527145, 2016). "In conclusion, it has been hypothesized that very low leptin concentration, as a signal of energy insufficiency, would suppress the reproductive function at the HPG level, while elevated leptin levels, such as those observed in obesity, may have direct inhibitory effects on the gonads." (PMID 26875986, 2016). "Thus, RNF11 represent a further molecular detail how hypothalamic inflammation may trigger leptin resistance and obesity in the very early days of high caloric intake." (PMID 27551276, 2016). "Many factors related to breastfeeding may influence childhood weight outcomes and obesity such as breastfeeding duration; however, it should be considered that, ingesting high amounts of leptin, infants with obese mothers become leptin resistant and have alterations in appetite regulation." (PMID 27338468, 2016).
Obesity (continued). "These improvements in glucose homeostasis in the F-FOPS mice might be due to enhanced SCFA production from the FOPS fermentation as butyrate and propionate have been shown to protect against diet-induced obesity as well as reduce fasting insulin and leptin levels." (PMID 26731528, 2016). "We then asked whether treatment of exogenous LEP can rescue the obesity phenotype." (PMID 27378381, 2016). "Interestingly, there are also findings which show similar patterns of changes in plasma leptin and adiponectin concentrations in obesity despite the increase in adiposity, suggesting that decreased adiponectin synthesis or secretion by adipocytes occurs in obese states." (PMID 26731409, 2016). "Therefore, re-establishing leptin sensitivity by reducing the hyperleptinemia may represent a novel approach to treat obesity also in PWS." (PMID 27900261, 2016). "Studies related to gut and adipose tissue hormones and obesity suggest that obesity is associated with a blunted postprandial response of satiety factors such as GLP-1 and PYY, CCK and reduced postprandial suppression of orexigenic ghrelin, and some type of central leptin resistance." (PMID 26499438, 2016). "Adipokines, such as leptin, may affect cancer through its link with inflammation and obesity." (PMID 26632325, 2016). "The objective of this study was to test the hypothesis that high maternal concentrations of leptin during pregnancy, which are present in mothers with gestational diabetes and/or obesity, alter blood pressure, vascular structure and vascular function in offspring." (PMID 27187080, 2016). "In support of leptin's modulatory role on these distinct neuronal populations are mouse models that show that the obesity syndrome classically studied in leptin-deficient mice (Lepob/ob), when crossed with NPY-null mice, reduces obesity as compared with Lepob/ob mice alone." (PMID 26819774, 2016). "Indeed, leptin resistance, i.e., the inability of high circulating leptin levels to reduce food intake by a commensurate amount and increase energy expenditure is a near-universal feature of human obesity." (PMID 27445662, 2016). "Of interest, adiponectin and leptin have also been implicated in obesity-associated cancer; however, we did not observe any differences in the DNA methylation status of genes involved in leptin or adiponectin pathways in any of the esophageal tissue sets in the high vs. low BMI subjects." (PMID 27795744, 2016). "Therefore, drugs facilitating the alleviation of leptin resistance may benefit the treatment of obesity." (PMID 27444146, 2016). "However, some new studies question whether resistance to endogenous leptin contributes to development of diet-induced obesity in mice." (PMID 27579023, 2016). "Additionally, some other mechanisms are known, including dysfunction in the renin-angiotensin-aldosterone system, increased tubular sodium reabsorption, and the effects of obesity-related hormones and cytokines such as leptin, adiponectin and Tumor Necrosis Factor-α." (PMID 27832768, 2016). "On the other hand, higher serum leptin was inversely associated with cancer death in women with or without general obesity, for example, HR among women with BMI <30 kg/m2 was 0.76 (95% 0.44–1.32) and 0.30 (0.14–0.65) for moderate and high levels compared to low leptin, respectively (Ptrend = 0.003)." (PMID 26632325, 2016). "Accurate analysis of whole HM leptin will assist in clarifying the biological role of this milk component for the breastfed infant, improving our understanding of early developmental programming of appetite and its implications for obesity prevention later in life." (PMID 27834797, 2016). "The absence of leptin or mutations in its receptor induce obesity and hyperphagia." (PMID 27746590, 2016). "Leptin resistance may occur in obesity 36, where higher levels of leptin follow." (PMID 26632325, 2016).
Obesity (continued). "Although we could not identify the underlying mechanism or the link among resistin, leptin, and CD163/CD68 expression levels, our data suggest that serum resistin levels and leptin levels have specific roles in the regulation of ATM in patients with modest obesity." (PMID 27101398, 2016). "In this study, we established a mouse model to address the role of the hormones insulin, leptin, and adiponectin for the intergenerational EI of metabolic phenotypes in the absence of obesity and most of its associated complications, such as low grade inflammation." (PMID 26662513, 2016). "Therefore, it may induce GRP78, thereby ameliorating ER stress-induced leptin resistance in obesity." (PMID 27677243, 2016). "In addition, leptin may mediate the impact of obesity in this event: it has proved to increase CYP17A1 activity in vitro, although its significance in vivo during adrenarche is undetermined." (PMID 26697222, 2015). "In addition, fucoxanthin might alter the plasma leptin level in order to achieve its anti-obesity action." (PMID 26437420, 2015). "Leptin, as a pro-inflammatory adipokine, could be secreted excessively in obesity by adipocytes." (PMID 25890172, 2015). "Genes functioning in the leptin-melanocortin pathway such as those encoding leptin (LEP), leptin receptor (LEPR), melanocortin 4 receptor (MC4R), pro-opiomelanocortin (POMC) and brain-derived neurotrophic factor (BDNF) have been implicated in the monogenic form of obesity." (PMID 26363598, 2015). "Further analysis of BBS resulted in development of BBS knockout mice (Bbs2, Bbs4 and Bbs6) that developed hyperphagia, reduced energy expenditure and increased circulating leptin levels, which suggests that leptin deficiency is not the mechanism of obesity in BBS." (PMID 25825681, 2015). "Being an adipokine, leptin levels rise with increasing BMI and body fat, but its relation with diabetes and insulin resistance seems to be intriguing, as individuals who have both obesity and type 2 diabetes exhibit higher leptin levels when compared to obese or diabetic population alone." (PMID 25897417, 2015). "The results highlight the potential role of leptin during the suckling period, which might be worth considering when searching for strategies to treat and/or prevent the programmed trend to obesity acquired by inadequate fetal nutrition, particularly in susceptible subgroups." (PMID 25766068, 2015). "By contrast, the environmental chemical pollutant tributyltin chloride, which inhibits the ATP synthase of the oxidative phosphorylation system, can promote adipocyte differentiation and leptin secretion, leading to obesity and metabolic syndrome as postulated by the obesogen hypothesis." (PMID 26398948, 2015). "This is of particular interest in the context of metabolic disease, since altered leptin profiles (such as leptin resistance, insufficient or dysfunctional leptin production or signalling) accompanying obesity may interact with the HPA axis in order to contribute to metabolic disorder." (PMID 26000016, 2015). "In addition, assuming that brain structures regulating FAA are not leptin-resistant, diet-induced obesity in rats is another condition associating reduced FAA with increased adiposity and high levels of circulating leptin." (PMID 25970608, 2015). "Leptin may also have an impact on the airway milieu in asthmatics with obesity." (PMID 26770217, 2015). "In addition, overweight or obesity results in a higher level of adipocyte-derived leptin, which promotes cell proliferation, and a lower level of adiponectin, which may have anti-proliferative effects." (PMID 26684001, 2015). "Hence, better understanding of FPLD, a natural single-gene model of MS, could be the key to unlock leptin resistance in obesity, allowing leptin to perform its insulin-sensitizing function." (PMID 25859279, 2015).
Obesity (continued). "Other two interesting peptide hormones present in breast milk and provided to infants by mothers are ghrelin and adiponectin, which may contribute, together with leptin, to long-term control of appetite and may be also involved in the protection against obesity." (PMID 26680765, 2015). "Fucoxanthin might alter plasma leptin level in order to achieve the anti-obesity action." (PMID 25871295, 2015). "This review summarizes the existing literature on the effects of oxytocin administration in the treatment of obesity in different animal models and in humans, focusing on the central control of food intake, the oxytocin effects on adipose tissue, and the relationships between oxytocin and leptin." (PMID 26300847, 2015). "Given our discussion above on the importance of the renal sympathetic nerve responses in the potential for leptin to contribute to obesity-induced hypertension, the similar sympatho-excitatory actions of resistin and leptin on renal sympathetic nerve activity could assume greater significance." (PMID 26617526, 2015). "However, how obesity contributes to pulmonary diseases and whether leptin directly regulates lung inflammation remains unclear." (PMID 26593914, 2015). "Therefore, rapamycin may be used as an anti-leptin agent for the prevention and intervention against obesity-related pancreatic cancer." (PMID 25948792, 2015). "However, lower level of physical activity probably also contributes to the obesity in the ob/ob mice, since leptin is involved in regulation of energy expenditure, and we observed that the ob/ob mice were much less physically active than the ob/wt and wt/wt mice." (PMID 26347815, 2015). "Within the central nervous system, diet-induced obesity does not uniformly cause leptin resistance." (PMID 26236282, 2015). "Therefore, in the present study, the effects of metformin on amelioration of adipokine imbalance, such as decreasing leptin but increasing adiponectin in serum, may prevent obesity- and diabetes-related liver tumorigenesis." (PMID 25879666, 2015). "In addition, leptin presents various functions in the immune system, including inflammation, and plays a major role in the chronic pro-inflammatory state that is seen in obesity and atherosclerosis." (PMID 25453257, 2015). "For example, studies demonstrating that tanycytes are responsible for leptin transport into the brain suggest that they may be a potential therapeutic target for the treatment of leptin resistance in obesity through increasing their transport of this hormone into the hypothalamus." (PMID 25859240, 2015). "In addition, BC improved obesity parameters such as leptin and adipocyte size." (PMID 26504474, 2015). "Interestingly, leptin can be considered one of the common denominators of IR in LD and obesity." (PMID 25859279, 2015). "To study the mechanisms underlying the leptin-miR21 axis we used toxin-induced experimental NASH models (Bromodichloromethane and Carbon tetrachloride) which included oxidative stress as a second hit in an underlying condition of obesity and insulin resistance." (PMID 25658689, 2015). "One hallmark of obesity is a systemic low-grade inflammation with increased levels of many inflammatory markers such as C-reactive protein (CRP), interleukin- (IL-) 6, tumor necrosis factor- (TNF-) α, and leptin, and this is maybe important for the pathogenesis of obesity-related asthma." (PMID 26538828, 2015). "Bilirubin treatment significantly reduced leptin and slightly increased adiponectin levels 14 days post treatment, which supports the hypothesis that the effects of bilirubin on obesity and insulin resistance are, at least in part, mediated by leptin and adiponectin." (PMID 26017184, 2015). "The inhibition of leptin gene expression by Adv36 infection may increase lipid accumulation and obesity prevalence reported that human cells infected with Adv36 showed greater differentiation and higher levels of lipid accumulation than non-infected control cells." (PMID 26184280, 2015).
Obesity (continued). "Furthermore, obesity-related overproduction of leptin in SAT could be one of the drivers of the upregulation of the Th17 pathway, further highlighting the potential contribution of the SAT, besides that of the AAT." (PMID 26229237, 2015). "Leptin plasma concentrations are increased in obese subjects (leptin resistance is suspected) and has both anorexigenic and proinflammatory properties, whereas adiponectin improves insulin sensitivity, exerts anti-inflammatory actions and its secretion is significantly reduced in obesity." (PMID 25929254, 2015). "Thus, we hypothesize that leptin and resistin, when present in high concentrations, may act together and contribute to obesity-induced hypertension and renal dysfunction." (PMID 26617526, 2015). "In contrast to the proinflammatory effects of leptin, adiponectin is predominantly an anti-inflammatory mediator, mainly involved in glucose control and fatty acid metabolism, that is synthesized in adipose tissue and plasma levels of adiponectin are decreased in obesity." (PMID 26770217, 2015). "The juxtaposition between our results and those from the leptin knockout mice suggests that obesity per se might not be the cause changes in muscle fiber type, but these alterations may be linked more directly to the effects of leptin itself." (PMID 24744883, 2014). "We recently addressed the issue of metabolic reprograming in obesity-associated CRC and demonstrated that secreted products from the adipose tissue of obese subjects inhibit mitochondrial respiration and function in HCT116 colon cancer cells, an effect that is at least partly mediated by leptin." (PMID 25019059, 2014). "Thus, the dysregulation of leptin actions, e.g., changes in leptin receptor expression in adipose tissue, may influence obesity and other metabolic disorders development, such as insulin resistance and type II diabetes." (PMID 24243000, 2014). "Conversely increased leptin ingestion may enhance satiety, reducing intake and later obesity." (PMID 25536196, 2014). "Therefore, specific small molecule inhibitors such as KMU-3 identified in this study are useful leads for future drug development efforts for prevention and/or treatment of obesity and/or obesity-related disease in which overexpression of leptin, RBP4, and/or RANTES plays pathological roles." (PMID 25285517, 2014). "Moreover, the discovery of leptin can be framed as identification of the gene long known to be involved in obesity, therefore falling into the category of specific hypothesis-driven research." (PMID 25177314, 2014). "The absence of leptin signaling in leptin-deficient ob/ob or leptin receptor (LepRb)-null db/db mice promotes hyperphagia and decreased energy expenditure (with consequent obesity)." (PMID 24424041, 2014). "The adipokine leptin, which is secreted in proportion to adipocyte mass, may have a key role in mediating adipocyte-T cell interactions in both obesity and malnutrition, and has been shown to promote effector T cell function and metabolism while inhibiting regulatory T cell proliferation." (PMID 25157251, 2014). "These experimental and clinical studies indicate that the NO-dependent vasodilatory effects of leptin become impaired, and by this mechanism, leptin may contribute to endothelial dysfunction and the progression of atherosclerosis in patients with obesity and/or MetS." (PMID 24410779, 2014). "Meanwhile, data began accumulating on the pathophysiological changes in leptin production and signaling that take place in obese subjects, eventually leading to realization of the unfeasibility and lack of strong biological basis for using leptin as a therapeutic approach to obesity." (PMID 25177314, 2014). "Moreover, the role of leptin and Treg in the progression of obesity-related diabetes is yet to be fully elucidated and may provide even more targets for future drug research." (PMID 25477880, 2014).